NOTCH3 (notch receptor 3)
Diseases named in the same sentence as NOTCH3 in open-access papers (continued):
Sharing a sentence is not in itself a finding about the gene and the disease.
melanoma (continued). "NOTCH3 mediates the communication between melanoma cells and endothelial cells, thus promoting tumor cell migration." (PMID 37217516, 2023). "These experiments identified proteins called MMP14, Notch3, and β1-integrin as critical to the invasive spread of melanoma cells." (PMID 29712618, 2018). "When melanoma cells with less MMP14 or Notch3 were implanted into zebrafish, the cancer cells spread less efficiently." (PMID 29712618, 2018). "This suggests that the LEC-induced transient, invasively sprouting phenotype of melanoma cells is mediated by activated Notch3 and β1-integrin both dependent on the key upstream regulator MMP14." (PMID 29712618, 2018). "Notch3 depletion almost completely abolished the increase in the sprouting growth of the LEC primed WM852, further supporting the role of Notch3 for the switch to the sprouting 3D growth of melanoma cells induced by LEC interaction." (PMID 29712618, 2018). "(f) Representative confocal images of Notch3 staining (red) in different GFP expressing melanoma cell lines (GFP positive cells shown in the inset) cultured in the presence (*) or absence of LECs." (PMID 29712618, 2018). "Previous studies using co-culture of HUVECs and melanoma cells have identified Notch3 as a player in melanoma–EC communication and a potential mediator of melanoma metastasis also in human tumors." (PMID 29712618, 2018). "Several studies indicated that miR-206 induces G1 arrest in melanoma cell lines and function as a pro-apoptotic factor in HeLa cells through targeting Notch3 signal pathway." (PMID 28615991, 2017). "These melanoma-private mutations occurred in genes linked to chromatin regulation (ARID1A and ARID2), cell growth (e.g., PIK3CA), cell adhesion (e.g., EPHA2), splicing (SF3B1), angiogenesis (PTPRB), and classic tumor suppressors (NOTCH3, CDKN2A, and PTEN)." (PMID 41516405, 2026). "In addition, DLL4 was recently identified as a an upstream inducer of the Notch3/WNT5B axis mediating bidirectional prometastatic crosstalk between melanoma and lymphatic endothelial cells." (PMID 39951484, 2025). "Accumulating evidence supports the contribution of Notch3 to the aggressiveness of melanoma." (PMID 37971882, 2024). "Interestingly, the full-length Notch3 receptor level was also increased by DLL1-Fc and DLL4-Fc treatments, which together with the observed increase in the mRNA levels suggest that Notch3 is induced through an autoregulatory loop in the melanoma cells." (PMID 37971882, 2024). "Finally, DLL4, a Notch ligand expressed in LECs, was identified as an upstream inducer of the Notch3/WNT5B axis in melanoma." (PMID 37971882, 2024). "Induced NOTCH3 signaling in melanoma cells enhanced tumor cell migration while causing no significant increases in tumor cell growth." (PMID 37217516, 2023). "Moreover, the LncRNA BASP1-AS1 regulates the transcription of Notch3 by interacting with YBX1 in melanoma." (PMID 37253771, 2023). "Moreover, NOTCH3 was considered as a molecular switch driving melanoma heterogeneity since the knockdown of NOTCH3 in melanoma cell lines retarded and abolished tumorigenicity." (PMID 37217516, 2023). "Then, we identified 9 LR pairs (“BMP6- > HJV” 、"CCL8- > ACKR4” 、"DLL3- > NOTCH3"、"DSC3- > DSG3"、"GHRH- > GHRHR” 、"LRRC4B- > PTPRF"、"SEMA4D- > PLXNB1"、"SFRP1- > FZD6"、"UCN- > CRHR1′′) as key LR pairs in melanoma prognosis through Lasso Cox regression and Multiple Stepwise Regression." (PMID 36777724, 2023). "NOTCH3 also plays an essential role in the development of melanoma." (PMID 33748290, 2021). "The NOTCH3 signaling pathway may promote melanoma stem-like cells' plasticity and niche morphology in an environment-dependent manner." (PMID 33748290, 2021). "Additionally, the interactions between CSCs and ECs activate Notch3 signaling to promote angiogenesis and vasculogenic mimicry in melanoma." (PMID 34195229, 2021).
melanoma (continued). "We found that the interaction of melanoma cells with LECs induced matrix-metalloproteinase-14 (MMP14, also known as MT1-MMP) -dependent Notch3 and β1-integrin activation in the expansively growing metastatic melanoma cells, leading to invasive sprouting of cells in 3D matrices." (PMID 29712618, 2018). "Furthermore, our results indicate that β1-integrin functions downstream of Notch3 in the LEC-primed melanomas." (PMID 29712618, 2018). "Moreover, PlexinD1 expression correlates with Notch1 and Notch3 in different cancer types, and its role in metastatic tumor progression has been further demonstrated in colon cancer, melanoma, and ovarian cancer." (PMID 29462871, 2018). "Therefore, we tested whether Notch3 would function as the upstream regulator of WNT5B expression in the cocultured melanoma cells." (PMID 37971882, 2024). "Therefore, a deeper knowledge of the upstream and downstream effects of Notch3 signaling in melanoma may provide better cues for targetable molecular candidates." (PMID 37971882, 2024). "In addition, we have previously shown that direct contact of melanoma cells with LECs strongly augments melanoma invasion and metastasis through induction of Notch3 in the melanoma cells that is dependent on matrix metalloproteinase 14 (MMP14, also known as MT1-MMP)." (PMID 37971882, 2024). "Notch3 binds to the WNT5B gene promoter region, thus confirming its role as a transcriptional activator of WNT5B in melanoma cells." (PMID 37971882, 2024). "We found that melanoma cells induced metastasis-promoting molecular and functional changes in LECs mediated by the DLL4/Notch3/WNT5B signaling axis." (PMID 37971882, 2024). "Here, we report that the DLL4/Notch3/WNT5B signaling axis induced upon melanoma cell and LEC interaction promotes melanoma metastasis via its effects on LEC phenotype and function." (PMID 37971882, 2024). "DLL4-Fc induced the expression of NOTCH3 mRNA in the metastatic melanoma cell lines WM852 and WM165, while DLL1 induced NOTCH3 only in WM165." (PMID 37971882, 2024). "Fifty-five primary tumor samples and 44 metastasis samples from these 55 melanoma patients were stained with antibodies against WNT5B and Notch3." (PMID 37971882, 2024). "WNT5B did not significantly correlate with patient survival, potentially due to Notch3 being the upstream regulator of WNT5B transcription and production in the melanoma cells." (PMID 37971882, 2024). "The results revealed that the CSTB, GBF1, TYR, RAC1, SLC2A1 and NOTCH3-coding proteins were significantly enriched in melanoma samples, while CEBPB-coding protein had low expression in melanoma samples." (PMID 37217516, 2023). "Five of nine identified ER stress-related genes, CEBPB, TYR, SLC2A1, NOTCH3 and RAC1, have been reported to engage in melanoma malignant behavior regulation." (PMID 37217516, 2023). "In summary, we found that NOTCH3, DBN1, KDELC2, and STAB1 were closely related to M2 macrophage infiltration in melanoma tissues." (PMID 33748290, 2021). "The yellow-green module was the coexpression module most related to M2 macrophages in TCGA-SKCM; NOTCH3, DBN1, KDELC2, and STAB1 were identified as the essential genes that promoted the infiltration of M2 macrophages in melanoma." (PMID 33748290, 2021). "They found that lymphatic endothelial cells promote melanoma metastasis and invasion by relying on MMP14, NOTCH3, and β1 integrin." (PMID 33748290, 2021). "We therefore next investigated if Notch3 and its downstream targets were induced in the LEC primed melanomas." (PMID 29712618, 2018). "We found that treatment of melanoma cells with SCH984 led to decreased Notch2 and Notch3 mRNA levels in responder cells, whereas Notch3 mRNA levels were not affected in the non-responder cells." (PMID 27655717, 2016). "NOTCH3 depletion in the monotypic melanoma cells, however, did not significantly affect the basal level of WNT5B." (PMID 37971882, 2024).
melanoma (continued). "We next investigated whether Notch3 and WNT5B expression would correlate in melanoma patient samples." (PMID 37971882, 2024). "When compared with vehicle-treated cocultures, the DAPT treatment significantly reduced the upregulation of WNT5B mRNA levels in WM852 and WM165 cells cocultured with LECs, further supporting a key role for Notch3 in regulating WNT5B expression in the metastatic WM852 and WM165 melanoma cells." (PMID 37971882, 2024). "Notch ligand DLL4 is a potent inducer of Notch3 and WNT5B in melanoma." (PMID 37971882, 2024). "Furthermore, expression of Notch3 and WNT5B shows a significant, positive correlation at the mRNA level in a 442-patient melanoma data set obtained from The Cancer Genome Atlas (TCGA)." (PMID 37971882, 2024). "In these studies, we demonstrated the role of NOTCH3, DBN1, KDELC2, and STAB1 in melanoma patients." (PMID 33748290, 2021). "Importantly, the interaction of these melanoma cells with LECs led to significantly increased metastasis of melanoma xenografts in vivo, which was dependent on MMP14 and Notch3." (PMID 29712618, 2018). "Notably, the expansively growing metastatic melanoma cells adopted an invasively sprouting phenotype in 3D matrix that was dependent on MMP14, Notch3 and β1-integrin." (PMID 29712618, 2018). "However, as our transcriptomic data of the LEC-primed melanoma cells did not reveal changes in ICAP-1 expression upon LEC-priming it probably does not play a significant role in the Notch3-dependent invasive sprouting of metastatic melanoma cells." (PMID 29712618, 2018). "Moreover, WNT5B transcription was regulated by Notch3 in melanoma cells following the coculture with LECs, and Notch3 and WNT5B were coexpressed in melanoma patient primary tumor and metastasis samples." (PMID 37971882, 2024).
non-small cell lung carcinoma (21 papers, 2009 to 2026). A group of at least three distinct histological types of lung cancer, including non-small cell squamous cell carcinoma, adenocarcinoma, and large cell carcinoma. "Previous studies in cancer cells found that Notch3 regulates lipid peroxidation and reactive oxygen species, and a loss of Notch3 function induced ferroptosis in non-small cell lung cancer cells." (PMID 37895313, 2023). "The upregulation of STRAP correlates with ICN3 (intracellular fragment of Notch3) in 59% of non-small-cell lung cancers and increases its stabilization." (PMID 40558481, 2025). "STRAP interacts with Notch3 and stabilizes it by inhibiting its proteasomal degradation, and they are co-upregulated in non-small cell lung carcinoma." (PMID 40558481, 2025). "Evodiamine, an alkaloid derived from Euodiae Fructus, has low toxicity and suppresses Notch-3 by activating DNA methyltransferase 3A induced Notch-3 methylation in non-small-cell lung cancer." (PMID 37308977, 2023). "As a result, siRNAs or γ-secretase inhibitors targeting NOTCH3 are currently under investigation to overcome therapy resistance and sensitize pancreatic and non-small cell lung cancer to treatment with gemcitabine." (PMID 36749424, 2023). "It is clear from all the evidence that not only Notch3 contributes to the occurrence and development of non-small cell lung cancer but also related proteins within its pathway are involved in drug resistance and recurrence." (PMID 35463301, 2022). "Recent findings indicate that Notch3 overexpression not only is responsible for the initiation of non-small cell lung cancer, but also can reduce the expression of E-cadherin, upregulate fibronectin, and promote EMT and tumor invasion." (PMID 35463301, 2022). "Notch3 is required for tumor propagation in mouse models of non-small-cell lung cancer and human non-small-cell lung cancer." (PMID 28416766, 2017). "Because of the notorious toxicity and lack of survival benefit of γ-secretase inhibitors in clinical application, we evaluated evodiamine, a specific Notch-3 inhibitor that was reported to reverse tumor growth in non-small cell lung cancer with minimal side effects." (PMID 37308977, 2023). "NOTCH3 is unique, as it has been shown to be upregulated in non-small cell lung carcinoma in vivo." (PMID 35538551, 2022). "Likewise, in non-small cell lung cancer (NSCLC), expression of NOTCH3 was associated with poor survival of patients while in gastric cancer, high expression of all four NOTCH isoforms correlated with a short relapse-free survival." (PMID 33530306, 2021). "In fetal lung development, Notch signalling appears to be essential for the lung to achieve its normal size and Notch 1 and Notch 2 protein are frequently expressed in human non-small cell lung cancer with Notch3 mRNA expression being detected in 7 of 25 NSCLC cell lines." (PMID 19812696, 2009). "In a similar study, investigators report NOTCH3 expression negatively regulates ROS-mediated lipid peroxidation in non-small cell lung carcinoma (NSCLC), increasing tumorigenesis." (PMID 40502769, 2025). "Importantly, in mouse models of non-small cell lung cancer, disruption of the NOTCH3 enhancer significantly suppresses tumor progression and augments the anticancer effects of cisplatin, demonstrating the important role of the NOTCH3 enhancer in tumorigenesis and drug resistance." (PMID 38135679, 2023). "Although NOTCH signalling is implicated in both small cell lung cancer (SCLC) and non-small cell lung carcinoma (NSCLC), NOTCH3 is primarily over-expressed in NSCLC (Ref." (PMID 36052538, 2022). "NOTCH3 signaling is mainly expressed in non-small cell lung carcinoma (NSCLC), and has been proposed as a therapeutic target of NSCLC." (PMID 29765324, 2018).
gastric cancer (20 papers, 2005 to 2025). A primary or metastatic malignant neoplasm involving the stomach. "Notch 3′s high mRNA expression was only associated with worsen OS in surgery alone gastric cancer patients, HR 1.42 (1.00–2.02), p = 0.048." (PMID 27363496, 2016). "Notch 3 and Notch 4′s high mRNA expression is only associated with worsen OS in surgery alone for gastric cancer patients." (PMID 27363496, 2016). "In addition, it is reported that Notch3 and Jagged2 are not only associated with the development of gastric carcinoma but are also involved in intestinal glandular differentiation of gastric carcinoma cells." (PMID 28881855, 2017). "In conclusion, we highlighted the critical role of NOTCH3 in linking depression and gastric cancer progression." (PMID 40940884, 2025). "This work identifies the estrogen/NOTCH3 signaling as a key link between depression and gastric cancer, offering promising therapeutic strategies to improve outcomes for patients suffering from depression." (PMID 40940884, 2025). "Through Western blot and qPCR experiments, we assessed the expression of NOTCH3 in gastric cancer cells, revealing a significant increase in both gene transcription and protein levels within the HGC-27 cell line." (PMID 38906903, 2024). "When combined, our findings demonstrated that gastric cancer cells have significantly elevated NOTCH3 mRNA and protein expression." (PMID 38906903, 2024). "To investigate the expression trends of NOTCH3 and immune infiltration-related factors in gastric cancer cells, we examined the protein expression of NLRP3, COX-2, and NF-κB p-p65 in HGC-27 cell line and normal gastric tissue." (PMID 38906903, 2024). "Using real-time PCR and western blot analysis, we first examined NOTCH3 mRNA and protein expression in the stomach tissue of normal rats and the human gastric cancer cell line HGC-27 to ascertain if NOTCH3 is involved in the formation of gastric cancer." (PMID 38906903, 2024). "The results show that novel insights in the functional role of NOTCH3 in gastric cancer, thereby highlighting a potential mechanistic basis whereby NOTCH3 influences immune cell interaction in tumors." (PMID 38906903, 2024). "In general, more studies are needed to find NOTCH3-related pathways in increasing gastric cancer invasion." (PMID 34054953, 2021). "Notch3 and Jagged2 were found to contribute to the development and glandular differentiation of gastric cancer, together with MUC5AC." (PMID 28938681, 2017). "In this report, our results show that Notch3′s high mRNA expression was significantly correlated to worsen OS for all gastric cancer patients, as well as in intestinal type cancer patients and diffuse type cancer patients." (PMID 27363496, 2016). "HPV capsid proteins L1 and L2 may induce virus internalization, probably through the attachment to neurogenic locus notch homolog protein 3 (NOTCH3) or EPH receptor B2 (EPHB2) in gastric cancer." (PMID 39228892, 2024). "High NOTCH3 expression significantly correlates with poor survival of gastric cancer patients." (PMID 35136410, 2022). "Notch 3′s high mRNA expression is only significantly associated with worsen OS in HER2 negative gastric cancer patients." (PMID 27363496, 2016). "Same as Notch3, the study about Notch4 in gastric cancer is also limited." (PMID 27363496, 2016). "Notch 3′s high mRNA expression was only significantly associated with worsen OS in HER2 negative gastric cancer patients, HR 1.57 (1.22–2.01), p = 0.00043." (PMID 27363496, 2016). "Notch3′ high mRNA expression was found to be significantly correlated to worsen OS for all gastric cancer patients, HR 1.6 (1.31–1.97), p = 5.3e-06, as well as in intestinal type cancer patients, HR 2.03 (1.36–3.03), p = 0.00039, and diffuse type cancer patients, HR 1.5 (1.06–2.11), p = 0.02." (PMID 27363496, 2016).
gastric cancer (continued). "In this study, we found that all the individual Notch receptors except Notch 3 are significantly associated with worsen OS in either HER2 negative or HER2 positive gastric cancer patients." (PMID 27363496, 2016). "Moreover, multivariate Cox regression analysis of the gastric cancer patients' clinical features revealed that NOTCH3 expression might be used as an independent prognostic factor." (PMID 35136410, 2022). "Among these cytokines, Notch‐3, galectin‐8, EphA1, epiregulin, and FGF‐12 have been reported to be upregulated in gastric cancer." (PMID 30873760, 2019). "Furthermore, we detected the upregulation of several interesting genes that have not been reported as being expressed in gastric cancer, such as CPE-R, Rvp.1, sarcolectin, KOC, Notch3, and maspin." (PMID 15770218, 2005).